BAG1 (BAG cochaperone 1)
Diseases named in the same sentence as BAG1 in open-access papers (continued):
Sharing a sentence is not in itself a finding about the gene and the disease.
lung cancer (7 papers, 2002 to 2021). A malignant neoplasm involving the lung. "We previously reported that BAG-1 overexpression in a large number of lung cancers is linked to improved patient prognosis." (PMID 22567091, 2012). "The increased expression of FLJ20420 corresponded to a significant decrease in BAG-1 protein expression in the primary lung cancers, relative to the paired normal lung tissue controls (p = 0.0001)." (PMID 22567091, 2012). "Current studies in our laboratory seek to unravel the mechanisms by which FLJ20420 regulates the expression of BAG-1 and its isoforms, as well as additional apoptotic-related proteins in lung cancer and other malignancies." (PMID 22567091, 2012). "A deeper understanding of FLJ20420 in lung cancer and other malignancies is important in the development of BAG-1-targeted therapy to improve the prognosis and treatment of patients with cancer." (PMID 22567091, 2012). "As expected, experiment performed in lung cancer cells indicates silencing of BAG-1 gene can sensitize lung cancer cells to cisplatin-induced apoptosis." (PMID 22439756, 2012). "Next, we determined the expression of FLJ20420 and BAG-1 genes in primary lung cancer tissues and the corresponding paired normal controls." (PMID 22567091, 2012). "Furthermore, Western blot analysis was also used to investigate BAG-1 protein expression in all of the lung cancer cell lines." (PMID 22567091, 2012). "Functional analysis of FLJ20420 revealed that this protein downregulates BAG-1 expression in lung cancer cell lines, suggesting that it may play a role in the regulation of BAG-1 expression in human carcinogenesis." (PMID 22567091, 2012). "Next, the expression of FLJ20420 and BAG-1 in human lung cancer cell lines was investigated." (PMID 22567091, 2012). "Further study showed that BAG-1 could be a target for lung cancer treatment of cisplatin." (PMID 22439756, 2012). "Because of its affect on apoptosis, BAG-1 may play an important role in lung cancer." (PMID 22439756, 2012). "We also observed a concordant decrease in BAG-1 expression and increase in FLJ20420 expression in lung cancer cell lines and the paired normal tissue controls." (PMID 22567091, 2012). "It will be interesting to determine the expression of these cytokines in these paired lung cancer and normal tissue samples, to correlate their expression to FLJ20420 and BAG-1 expression, and also to analyze their expression in a large number of lung cancer patient samples." (PMID 22567091, 2012). "Similarly, a higher level of BAG-1 protein was observed in the lung cancer cell lines GLC82, LTEP-2, SPCA-1, NCI-H446, YTLMC-9 and A549, which corresponded to increased BAG-1 mRNA expression." (PMID 22567091, 2012). "Restoration of SIX3 in lung cancer cells lacking endogenous SIX3 suppressed cell proliferation and migration, and downregulated a number of genes involved in proliferation and metastasis such as S100P, TGFB3, GINS3 and BAG1." (PMID 23977152, 2013).
prostate carcinoma (7 papers, 2009 to 2025). A carcinoma that arises from epithelial cells of the prostate gland. "BAG-1L plays a critical role in transactivation of the AR and nuclear BAG-1 protein expression correlates with important clinical characteristics in prostate cancer." (PMID 38412481, 2024). "We stably transfected 22Rv.1 prostate cancer cells with a construct coding for an HA-tagged Bag-1 peptide or an empty vector as control and treated the cells with thapsigargin that induces stress by calcium depletion from the ER." (PMID 23049684, 2012). "To determine the selectivity of the Bag-1 peptide toward inhibition of prostate cancer cell growth, we overexpressed the 19-mer in a series of benign prostate cells and prostate cancer cell lines and performed clonogenic assays with these cells." (PMID 23049684, 2012). "The clinical relevance of BAG-1 isoforms in prostate cancer has been studied extensively by IHC." (PMID 38412481, 2024). "We therefore first investigated whether BAG1 played a role in the action of X15695 in the prostate tumor cells using BAG1 knockdown LNCaP prostate cancer cells." (PMID 37520743, 2023). "We first determined whether Bag-1 interacts with GRP78/BiP in a GST pull-down assay using lysate from 22Rv.1 prostate cancer cells." (PMID 23049684, 2012). "Importantly, the postulated inhibitor of BAG-1 isoforms, Thio-2, suppressed AR signaling and other important pathways implicated in the development and progression of CRPC to reduce the growth of treatment-resistant prostate cancer cell lines and patient-derived models." (PMID 38412481, 2024). "Bag-1 peptide ectopic expression in several malignant but not benign prostate cancer cell lines as well as in prostate cancer xenograft models reduces tumor growth by inhibiting GRP78 refolding activity and inducing CHOP-mediated apoptosis." (PMID 23403503, 2013). "Taken together, these studies confirm that Thio-2 inhibits AR signaling and decreases C-MYC expression to inhibit the growth of prostate cancer cell lines through a mechanism of action that, in these specific studies, appears to be independent of BAG-1 isoform function." (PMID 38412481, 2024). "Importantly, although probably independent of BAG-1 isoform function, Thio-2 suppressed AR signaling and other key prostate cancer signaling pathways to inhibit the growth of CRPC models." (PMID 38412481, 2024). "Having demonstrated that Thio-2 inhibits AR signaling and the growth of prostate cancer models independent of BAG-1 isoform function, we investigated whether its mechanism of action may be mediated through the AR NTD as it has previously been shown to inhibit AR NTD transactivation." (PMID 38412481, 2024).
breast tumors (6 papers, 2008 to 2022). "The purpose of the present study was to examine expression patterns of Bag-1 in a large cohort of breast tumors and to assess the association with Bcl-2, estrogen receptor, progesterone receptor and Her2/neu, and other clinical/pathological variables." (PMID 18430249, 2008). "Bag-1 and Bcl-2 expression in breast tumors is associated with improved outcome and steroid receptor positivity." (PMID 18430249, 2008). "In the METABRIC dataset, BAG-1 mRNA was significantly elevated in HER2+ breast tumors and predicted overall survival in a multivariate analysis (HR = 0.81; p = 0.022)." (PMID 26958811, 2016). "Moreover, Bag-1 expression was strongly positively correlated with ER and PR expression, but negatively correlated with Her2 expression in breast tumors." (PMID 31883527, 2019). "Moreover, a slight upregulation of the oncogene c-Myc, along with an undetectable level of breast tumor-related gene Bag-1 and TRPS-1, was observed in BME65Cs cells while these genes are all highly expressed in MCF-7." (PMID 20969773, 2010). "A statistically significant positive correlation of cytosolic BAG-1 immunostaining with Bcl-2 expression was found in 62 of 76 (82%) breast tumours coexpressing these proteins, suggesting that BAG-1 and Bcl-2 may be coregulated to some extent in early-stage invasive breast cancers." (PMID 28510570, 2017). "Analysis of the METABRIC patient cohort revealed that BAG-1 mRNA is increased in HER2+/ER+ as well as HER2+/ER- breast tumors compared to normal breast epithelium, and in HER2+ cell lines BAG-1 protein expression is elevated." (PMID 26958811, 2016). "We therefore next examined the co-expression correlation between HSPs and co-chaperones including HSP90 family (HSP90AA1, HSP90AB1), HSP70 family (HSPA1A, HSPA1B, HSPA8) and BAG family (BAG1, BAG2, BAG3) among 960 breast tumor samples registered in the Cancer Genome Atlas (TCGA)." (PMID 36114410, 2022). "We observed that Bag-1 is overexpressed in breast tumors in all molecular subtypes, i.e., regardless of their ER, PR and Her2 expression profile." (PMID 31883527, 2019).
gastric cancer (6 papers, 2002 to 2021). A primary or metastatic malignant neoplasm involving the stomach. "In gastric cancer, over-expression of BAG1 is associated with tumor progression and its silencing promotes gastric cancer cell apoptosis." (PMID 31626592, 2019). "BAG-1 has been reported to facilitate epithelial cell survival following detachment from the underlying extracellular matrix and to promote cell migration in human gastric cancer cells." (PMID 12402153, 2002). "In gastric cancer, BAG1 expression could be downregulated by microRNA-494, leading to decreased cell proliferation and enhanced apoptosis." (PMID 34234849, 2021). "As a kind of TCM extractive, Cinobufacini could suppress the cell proliferation of BGC-823 human gastric cancer cells via targeting BAG-1 (an antiapoptosis gene) and inhibit tumor growth and metastasis in xenograft models." (PMID 30254688, 2018).
acute myeloid leukemia (5 papers, 2011 to 2023). Acute myeloid leukemia (AML) is a group of neoplasms arising from precursor cells committed to the myeloid cell-line differentiation. "BCL2‐associated athanogene‐1 (BAG1) is a multi‐functional protein that is found deregulated in several solid cancers and in paediatric acute myeloid leukaemia." (PMID 34402163, 2021). "BAG1 expression is up-regulated in acute myeloid leukemia (AML), and its silencing promotes AML cell apoptosis." (PMID 31626592, 2019). "Here, BAG1 protein was found highly expressed in children with acute myeloid leukemia at diagnosis, and in a cohort of leukemic cell lines." (PMID 22016818, 2011). "This study found that FGNs could treat acute myeloid leukemia subtype 2 (AML-M2) by silencing five essential oncogenes (BAG1, MDM2, Bcl-2, BIRC5, and XIAP) in AML-M2." (PMID 36612296, 2023).
cervical carcinoma (5 papers, 2002 to 2025). A carcinoma arising from either the exocervical squamous epithelium or the endocervical glandular epithelium. "Notably, BAG2 expression was significantly reduced in cervical cancer, while no significant changes were observed in other BAG family members (BAG1, BAG3, BAG4, BAG5, and BAG6), suggesting a unique role for BAG2 in cervical cancer." (PMID 40364789, 2025). "Since BAG-1 is over-expressed in the human cervical cancer cell line HeLa, we attempted to identify proteins that bind to the BAG-1 promoter by Southwestern blot analysis, using the BAG-1 promoter as a probe to screen the Human HeLa 5′ stretch plus cDNA library, λTripIEx (Clontech)." (PMID 22567091, 2012).
gallbladder carcinoma (5 papers, 2015 to 2022). "It was also identified that Bag-1 (Bcl-2-associated athanogene-1) is a direct and functional target of miR-138 in gallbladder carcinoma." (PMID 25962180, 2015). "The results from this study indicate that the target gene of miR-138 Bag-1 can regulate the apoptosis-associated genes in gallbladder carcinoma cells." (PMID 25962180, 2015). "Moreover, the significant effects caused by overexpression of miR-138 on gallbladder carcinoma cell growth and apoptosis were reversed partially following restoration of the expression of Bag-1 with a consequential elevation of BCL-2 as well as a suppression of Bax and caspase-3 levels." (PMID 25962180, 2015). "One of the previous studies showed that the tumor suppressor hsa-miR-138 expression was decreased in the tumor tissues, and the regain of miR-138 expression enhanced apoptosis of gallbladder cancer through directly targeting the 3′-UTR sites of Bag-1." (PMID 37533517, 2022). "The overexpression of Bag-1 significantly reversed the inhibitory effect of miR-138 on the growth of gallbladder carcinoma cells and also, resulted in an inhibition of apoptosis induced by miR-138." (PMID 25962180, 2015). "As a result, we assessed the expression of Bag-1 in gallbladder carcinoma and found that Bag-1 was upregulated at the mRNA level in 37 (75%) gallbladder carcinoma tissues compared with adjacent non-neoplastic tissues (P<0.001)." (PMID 25962180, 2015). "The data suggests that the reduced expression of miR-138 and increased expression of Bag-1 are frequently observed in human gallbladder carcinoma specimens." (PMID 25962180, 2015). "We concluded that miR-138 directly targets Bag-1 in gallbladder carcinoma cells, thus, suppresses cancer cell growth and induces apoptosis." (PMID 25962180, 2015). "Compared with their paired normal gallbladder samples, the gallbladder carcinoma samples had decreased expression of miR-138 and increased expression of Bag-1." (PMID 25962180, 2015). "Also, BAG1 highly expressed in gallbladder carcinoma samples was inhibited by microRNA-138, increasing tumor cell proliferation." (PMID 34234849, 2021). "However, little is known about the expression and functional role of Bag-1 in gallbladder carcinoma." (PMID 25962180, 2015). "A correlation analysis between the expression of miR-138 and Bag-1 was performed, and the results showed that there is a significant inverse correlation between the mRNA expression levels of miR-138 and Bag-1 (Pearson’s correlation R = −0.58, P<0.05) in gallbladder carcinoma." (PMID 25962180, 2015). "Furthermore, a significant inverse correlation was observed between the expression levels of miR-138 and Bag-1 mRNA in the gallbladder carcinoma tissues." (PMID 25962180, 2015). "miR-138-5p could also suppress cell proliferation by targeting Bag-1 in gallbladder carcinoma." (PMID 27978829, 2016). "Here we found a significant elevation of Bag-1 in gallbladder carcinoma tissues compared with the paired non-tumor tissues." (PMID 25962180, 2015). "Although we partially demonstrated the functions and regulations of miR-138 and its target gene Bag-1, the relationships between the expression level of miR-138 and clinical characteristics and prognosis of patients with gallbladder carcinoma have not yet been investigated." (PMID 25962180, 2015).
non-small cell lung carcinoma (5 papers, 2002 to 2021). A group of at least three distinct histological types of lung cancer, including non-small cell squamous cell carcinoma, adenocarcinoma, and large cell carcinoma. "Although some inconsistencies have been reported, there appears to be broad agreement that BAG-1 is overexpressed in breast and non-small cell lung cancer and that this can correlate with clinical parameters and improved patient outcome." (PMID 12373595, 2002).
colon cancer (3 papers, 2018 to 2019). "The anti-Bag-1-siRNA plasmid was combined with magnetic gold nanoparticles and evaluated its tumor inhibitory effects in colon cancer mouse model, developed by giving 1 × 106 of LoVo cell (human colon cancer cell lines) into the right flank of the Balb/C nude mice (14–16 g) of 4–5 weeks old." (PMID 29861465, 2018).
glioma (3 papers, 2019 to 2022). A benign or malignant brain and spinal cord tumor that arises from glial cells (astrocytes, oligodendrocytes, ependymal cells). "As an autophagy-related gene, BAG1 is also considered to be an important prognostic factor in low-grade gliomas." (PMID 36291283, 2022). "After constructing the risk model, we screened out the signature composed of five ATGs (BID, BAG1, PTK6, NRG3, MAP1LC3C) with the best prognosis prediction performance, indicating these five ATGs play an important role in glioma." (PMID 33768004, 2021).
hepatocellular carcinoma (3 papers, 2015 to 2022). A malignant tumor that arises from hepatocytes. "Recent studies indicated that overexpression of Bag-1 is associated with poor prognosis and resistance to doxorubicin in human hepatocellular carcinoma." (PMID 25962180, 2015). "Aberrant expression of Bag-1 has been described in a variety of human malignancies, such as breast, lung, cervical, colorectal and hepatocellular carcinoma." (PMID 28826504, 2017).
invasive breast carcinoma (3 papers, 2002 to 2017). A carcinoma that infiltrates the breast parenchyma. "On chromosome 9 are located the tumor suppressor genes CDKN2A, PIPSK1B, BTEB1, RECK and BAG1, the latter associated with antiapoptotic functions and overexpressed in invasive breast carcinomas." (PMID 27325915, 2016). "In most studies that found significance, high levels of BAG-1 protein expression in invasive breast carcinoma positively correlate with improved patient survival outcomes or improved prognosis." (PMID 28510570, 2017). "Interestingly, several studies have reported that nuclear BAG-1 expression correlated with reduced survival in patients with invasive breast cancer and laryngeal cancer after radiation therapy." (PMID 12402153, 2002).
leukemia (3 papers, 2010 to 2023). A malignant (clonal) hematologic disorder, involving hematopoietic stem cells and characterized by the presence of primitive or atypical myeloid or lymphoid cells in the bone marrow and the blood. "BAG1 has recently been found implicated in the field of leukemia." (PMID 22016818, 2011). "The first evidence that BAG1 protein is over-expressed in a group of AML patients and leukemic cell lines with respect to healthy donors implied that BAG1 might contribute to leukemia pathogenesis." (PMID 22016818, 2011). "Finally, BAG1 was found able to affect leukemia cell fate by influencing the expression of anti-apoptotic proteins crucial for AML maintenance." (PMID 22016818, 2011). "Aberrant BAG1 protein expression in AML suggests it might play a role in leukemia phenotype maintenance." (PMID 22016818, 2011). "In the past, we showed that ART induced apoptosis in KG-1a leukemia cells, and that a number of apoptosis-regulating genes (LOC51272, CIDEB, PDCD2, BAG1, BAG3, MADD) correlated with cellular responses towards ART." (PMID 20428086, 2010). "A silencing approach was used for determining BAG1's role in AML, finding that its down-regulation decreased expression of BCL2, BCL-XL, MCL1, and phospho-ERK1/2, all proteins able to sustain leukemia, without affecting the pro-apoptotic protein BAX." (PMID 22016818, 2011).
lung adenocarcinoma (3 papers, 2010 to 2021). A carcinoma that arises from the lung and is characterized by the presence of malignant glandular epithelial cells. "BAG-1, BAG-2, BAG-5 might be the potential protective factors while BAG-4 is possible risk factor of lung adenocarcinoma." (PMID 20959066, 2010).
renal cell carcinoma (3 papers, 2015 to 2022). "The expression of hsa-miR-28-5p inhibits the proliferation of B-cell lymphoma and renal cell carcinoma cells by regulating the expression of BAG1 and RAP1B, respectively." (PMID 35027933, 2022). "In patients, miR-135a inhibits cancer cell proliferation and exhibits the properties of a tumor suppressor in renal-cell carcinoma, while its target oncoprotein BAG-1 increases more than 4 fold as determined by proteomics." (PMID 25952319, 2015).
adenoma (2 papers, 2004 to 2013). A neoplasm arising from the epithelium. "BAG1, coding for an anti-apoptotic protein, was found overexpressed in human non-functioning PAs by array analysis, and is also up-regulated in MENX-associated adenomas." (PMID 23756599, 2013). "Whether this effect on adenoma cell survival requires that BAG-1 interacts with C-Raf or Hsc70/Hsp70 or with both partners requires additional studies." (PMID 15560850, 2004). "Whereas BAG-1 heterozygosity did not affect the rate of cell proliferation or signaling through the mitogenic cascade in adenoma cells, it increased the rate of apoptosis." (PMID 15560850, 2004).
amyotrophic lateral sclerosis (2 papers, 2011 to 2024). Amyotrophic lateral sclerosis (ALS) is a neurodegenerative disease characterized by progressive muscular paralysis reflecting degeneration of motor neurons in the primary motor cortex, corticospinal tracts, brainstem and spinal cord. "Involvement of BAG1 in neurodegenerative disease has been documented for Alzheimer's and Huntington's disease as well as Amyotrophic lateral sclerosis." (PMID 21423662, 2011).
Cerebral ischemia (2 papers, 2020 to 2023). Restriction of arterial blood supply to the brain associated with insufficient oxygenation to support the metabolic requirements of the tissue. "Depending on the BAG1/BAG3 ratio and expression level of HDAC6, a switch from the ubiquitin-proteasome pathway to the autophagy-lysosome pathway occurs between 10 and 30 min during cerebral ischemia." (PMID 32089771, 2020).